NGF (nerve growth factor)
Diseases named in the same sentence as NGF in open-access papers (continued):
Sharing a sentence is not in itself a finding about the gene and the disease.
dementia (32 papers, 2008 to 2025). Loss of intellectual abilities interfering with an individual's social and occupational functions. "For example, obesity is associated with secretion of nerve growth factor, who has been proposed as a protector against dementia via the cholinergic system." (PMID 38520024, 2024). "Exceptions were the association for Beta-NGF and all-cause dementia as well as the associations of CCL3, CCL20, and IL20-RA with vascular dementia, which became statistically significant with the best fitting function." (PMID 36085081, 2022). "In summary, dementia has been reported to be associated with the down regulation of levels of NGF-BDNF-CREB, signaling which in turn it increases the mRNA expression level of apoptotic genes which leads to cholinergic dysfunction and memory deficit." (PMID 30018265, 2018). "Deficiency of TrkA expression/function, or deficiency of NGF transport, or maturation of NGF from proNGF have been linked to BFCN degeneration, as well as memory deficits both in animal models and dementia patients." (PMID 31233568, 2019). "Together, our results suggest that HJG possesses neurotrophic effects similar to those of NGF, and can ameliorate cognitive dysfunction in a rat dementia model via CREB activation." (PMID 29209220, 2017). "For example, we demonstrated that the Japanese herbal medicine Yokukansan can improve symptoms of dementia, and its action involves neurotrophic factors such as NGF." (PMID 29209220, 2017). "Erinacines promote nerve growth factor (NGF) synthesis, which suggests the application of H. erinaceus or its secondary metabolites for the treatment and prevention of dementia and further neurodegenerative diseases." (PMID 25404227, 2014). "Previously, we reported that receptors of the endoplasmic reticulum (ER) protein inositol 1,4,5-triphosphate (IP3) play a role in the potentiation of NGF-induced neurite outgrowth by the antidepressant fluvoxamine and anti-dementia drug donepezil." (PMID 21151481, 2010). "An ongoing gene therapy focusing on NGF-grafted autologous fibroblasts that are implanted into the basal forebrain of AD patients predicts a slower progression of the dementia, some cognitive improvement and sprouting of axons on the site of injection." (PMID 18184369, 2008). "We also found nerve growth factor (NGF) stimulators from the fruiting bodies and mycelia of Hericium erinaceus, and named them hericenones C to H and erinacines A to I, which stimulate the biosynthesis of NGF and are considered to be effective against dementia." (PMID 36978462, 2023). "Two proteins in our panel, NGF and Parkinson disease protein 7 (PARK7), have well-established connections to brain function and dementia." (PMID 37759795, 2023). "Both NGF and BDNF are affected early in the disease and this is thought to initiate a cascade of events which exacerbates pathology and leads to the symptoms of dementia." (PMID 22654716, 2011).
melanoma (32 papers, 1981 to 2025). A malignant, usually aggressive tumor composed of atypical, neoplastic melanocytes. "Inhibiting the NGF renders melanomas susceptible to immune checkpoint blockade therapy and fosters long-term immunity by activating memory T cells with low affinity." (PMID 40806192, 2025). "Subsequent studies have determined that p75NTR, a receptor for NGF, is highly upregulated in melanoma cells and associated with brain metastasis." (PMID 27598148, 2016). "The discovery of NGF as a signal that underlies the reprogramming process may yield novel strategies to treat aggressive melanoma." (PMID 29175861, 2018). "High expression of metastasis-associated CD271-responsive genes NEK2, RAD51AP1, TOP2A and NGF in drug-resistant MeWo cells and their drug-dependent regulation, may have consequences for the priming of melanoma cells for metastasis." (PMID 28112719, 2017). "Furthermore, among all neurotrophins, only NGF is associated with poor prognosis when expressed at high levels in melanoma specimens, as revealed by TCGA data analysis." (PMID 29215016, 2017). "Employing medicinal chemistry, a more potent derivative termed Np75-4A22 was identified that blocked nerve growth factor (NGF)-mediated melanoma invasion at sub-micromolar concentrations." (PMID 40962940, 2025). "Melanoma cells can express neurotrophic factors, such as the nerve growth factor (NGF) and brain-derived neurotrophic factor (BDNF), and their corresponding Tyrosine kinase receptors (TrkA and TrkB) that can be detected by immunohistochemistry." (PMID 40806192, 2025). "Higher expression of NGF was detected in melanocytic nevi during the early stages of neoplastic transformation to primary melanomas." (PMID 38359031, 2024). "In the present study we aimed to clarify the protein expression of NGF, proNGF and their receptors TrkA, p75NTR and sortilin in melanoma by using immunohistochemistry." (PMID 35457078, 2022). "Immunostaining was digitally quantified and revealed NGF and proNGF were expressed in all nevi and primary melanomas, and that the level of expression decreased from primary tumors to melanoma metastases (p = 0.0179 and p < 0.0001, respectively)." (PMID 35457078, 2022). "In this study we clarified the expression of NGF and its receptors TrkA and p75NTR in melanoma, and we reported, for the first time, the expression of proNGF and its membrane receptor, sortilin." (PMID 35457078, 2022). "Our data showed that p75NTR and sortilin were expressed in most primary tumors and metastases, whereas NGF/proNGF and TrkA were downregulated in primary melanoma and metastases." (PMID 35457078, 2022). "Together, it appears that the data about the expression of NGF, proNGF and their receptors in melanoma are incomplete and fragmentary." (PMID 35457078, 2022). "The five most enriched pathways (according to FDR corrected p-value) were pathways in cancer, signaling by interleukins, signaling by NGF, melanoma, and proteoglycans in cancer." (PMID 32917932, 2020). "With these in mind, we searched for molecular signs of neoneurogenesis in melanoma by estimating the levels of NGF, NGFR and BDNF, in conjunction with invasive phenotypes." (PMID 33339112, 2020). "To address this, we set up a time course experiment in which C8161 melanoma cells were exposed to NGF (200 ng/ml) for either 3 days (blue bar), 5 days (red bar) or 7 days (green bar), and counted Mart-1:GFP-positive cells every 24 h." (PMID 29175861, 2018). "We then tested the ability of NGF to attract C8161 metastatic melanoma cells by challenging plated spheres of cells with either a PBS or NGF-soaked bead." (PMID 29175861, 2018). "Our finding that NGF induced re-expression of key regulators in melanin production in amelanotic C8161 metastatic melanoma cells was suggestive of reprogramming towards a benign multipotent neural crest cell type." (PMID 29175861, 2018).
melanoma (continued). "When we exposed C8161 metastatic melanoma cells to each of these factors separately for 72 h, we found that NGF produced a significant increase in Mart-1 re-expression." (PMID 29175861, 2018). "For transplantation purposes, we added NGF to hanging drop cultures of C8161 metastatic melanoma cells." (PMID 29175861, 2018). "Given our findings that NGF has the ability to force Mart-1 re-expression, this lends the possibility of therapeutic approaches to modulating Mart-1 expression on metastatic melanoma cells, rendering them recognizable by cytotoxic T lymphocytes." (PMID 29175861, 2018). "Are the gene expression changes induced from NGF versus RA induced Mart-1:GFP re-expression in C8161 metastatic melanoma cells similar?" (PMID 29175861, 2018). "Compound 1 exhibited cytotoxicity against B16 melanoma cells and anti-bacterial activity against Bacillus subtilis, and enhanced the NGF-induced neurite outgrowth of PC12 cells." (PMID 28383484, 2017). "As regards the results of the biological tests, 1 showed the cytotoxicity against B16 melanoma cells, NGF neurite outgrowth promoting activity to PC12 cells, and growth inhibition against B. subtilis." (PMID 28383484, 2017). "It has been shown that NGF is able to induce invasion in melanoma cell lines and that this is dependent on the presence of CD27132,33." (PMID 29215016, 2017). "Similar results were reported in melanoma, expressing Trks, p75NTR and sortilin, wherein cell migration and invasion induced by pro-NGF were depending on p75NTR." (PMID 27120782, 2016). "In the mid-1970s, researchers noted that melanoma cells had a very high density of receptors for, and strong affinity towards, neurotrophins such as nerve growth factor (NGF)." (PMID 27598148, 2016). "Using an NGF ELISA assay, we observed that the concentration of NGF in melanoma tissue and serum is significantly higher than in counterpart control tissues." (PMID 19517020, 2009). "Collectively these data allow us to conclude that melanoma-derived NGF is a potentially important mediator in the downregulation of specific salivary transcriptome only in the melanoma-bearing mice." (PMID 19517020, 2009). "Collectively these data suggest that melanoma can produce NGF and is secreted it into the bloodstream." (PMID 19517020, 2009). "While NGF was detectable, it was at a significantly lower level than the melanoma tumor lysate (20.9±4.3 pg/mg in lung tumor vs. 75.73±24 pg/mg in melanoma tissue, P<0.05, data not shown)." (PMID 19517020, 2009). "The NGF drives immune cell exclusion in the melanoma tumor microenvironment." (PMID 40806192, 2025). "Nerve growth factor (NGF), through its receptor p75NTR, promoted the migration of melanoma cells." (PMID 35155573, 2022). "NGF immunohistochemical staining was observed in all cases of compound nevi, dysplastic nevi, thin primary melanomas, thick primary melanomas, lymph node metastases and distant metastases." (PMID 35457078, 2022). "NGF stimulation of TrkA and p75NTR also enhances proliferation and migration of melanoma cells." (PMID 35457078, 2022). "In melanoma, there have been some reports suggesting that NGF, TrkA and p75NTR are dysregulated, but the expression of the NGF precursor (proNGF) and its membrane receptor sortilin is unknown." (PMID 35457078, 2022). "This interaction facilitates the migration of melanoma cells in a NGF and pro-NGF dependent manner." (PMID 32878000, 2020). "To determine whether Mart-1 re-expression in C8161 metastatic melanoma cells could be extended beyond our initial observations of 72 h, we tested whether removal of NGF would affect the number of Mart-1:GFP-positive cells." (PMID 29175861, 2018). "After co-culturing C8161 metastatic melanoma cells with NGF for 72 h, we isolated Mart-1:GFP-positive re-expressing C8161 cells by FACS and compared gene expression profiles to wild-type C8161 and C81-61 cells using qPCR (using C8161 as baseline expression, light blue bar)." (PMID 29175861, 2018).
melanoma (continued). "To test whether NGF altered the proliferation of C8161 metastatic melanoma cells, we measured changes in proliferation in co-culture experiments with NGF, BDNF, CXCL12 and NT3 by BrdU incorporation (30-min pulse)." (PMID 29175861, 2018). "For example, given the established focal therapy of implanting radioactive seeds into the prostate gland, the use of ultrasound guidance may be used to deliver NGF beads into the melanoma microenvironment to drive tumor cell differentiation." (PMID 29175861, 2018). "After determining that C8161 metastatic melanoma cells express both NGF receptors, we used inhibitors to block each receptor individually, and in combination in co-culture experiments in the presence of NGF, and assessed the extent of Mart-1:GFP re-expression." (PMID 29175861, 2018). "In addition, we analyzed neurotrophins NT-3, NT-4, brain-derived neurotrophic factor (BDNF), and nerve growth factor (NGF) on mRNA level in seven melanoma cell lines compared to NHEM." (PMID 27901477, 2017). "NGF can stimulate the proliferation and metastasis of melanoma cells." (PMID 19517020, 2009). "In addition, the precursor for NGF (proNGF) can also regulate cell growth, but it is unknown if proNGF and its membrane receptor sortilin are also involved in melanoma." (PMID 35457078, 2022). "Notably, NGF mediates melanoma cell migration and metastasis." (PMID 28112719, 2017). "We therefore hypothesize that NGF is secreted into the circulation by the melanoma, circulates to the salivary gland where it activates the receptor-mediated signaling cascade leading to Egr-1 upregulation and induction of specific gene transcription and protein translation." (PMID 19517020, 2009). "Upon reaching the salivary glands, the increased NGF levels in the blood could then stimulate the increased expression of TFs such as Egr-1 leading to altered gene expression and protein profiles in the saliva of melanoma-bearing mice." (PMID 19517020, 2009). "To investigate whether the developed tumors can mediate the altered expression of TFs in the salivary glands of tumor-bearing mice, we examined the NGF/Egr1 signal pathway because Egr1 was identified as an up-regulated TF in the salivary gland of melanoma-tumor mice." (PMID 19517020, 2009). "Our data are in line with previous studies reporting a role of NGF and/or CD271 in mediating melanoma cell invasion in vitro and of neurotrophins and their receptors in promoting melanoma cell migration." (PMID 29215016, 2017). "Interestingly, astrocytes found at the stromal—tumor interface of melanoma brain metastases display increased expression of neurotrophins like NGF and NT-3, further supporting the hypothesis that these ligands originate from the brain and support melanoma cell metastasis." (PMID 27598148, 2016). "For this purpose, melanoma cell lines were exposed to various cytokines (EPO, EGF, TGF-ß1, Heregulin-α, IGF-1, HGF, SCF, NGF) and then were subjected to qPCR analysis and flow cytometry." (PMID 24489649, 2014). "In brain biopsies, increased amounts of nerve growth factor (NGF) and NT-3 were observed in tumor-adjacent tissues at the invasion front of human melanoma tumors." (PMID 22084751, 2011). "Together, these results pointed to a downregulation of NGF/ProNGF and TrkA in melanoma, and thus did not provide evidence to support the use of anti-proNGF/NGF or anti-TrkA therapies in advanced and metastatic forms of melanoma." (PMID 35457078, 2022). "NGF gene expression across melanoma stages was broader in range in stages 1–4 but not significantly different to stage 0." (PMID 35457078, 2022). "When both receptors were blocked simultaneously, we observed very few Mart-1:GFP-positive C8161 metastatic melanoma cells (0.2±0.2%, s.d., P=0.8), similar to control conditions without NGF (0.17±0.15%, s.d.)." (PMID 29175861, 2018).
melanoma (continued). "Keratinocyte-derived NGF (nerve growth factor) serves to counteract UV-induced depletion of melanocytes by increasing the level of the anti-apoptotic BCL-2 protein, a mechanism that might help melanoma cells bypass critical phases." (PMID 38473275, 2024). "With the observation of significant proliferation differences between Mart-1:GFP-positive and Mart-1:GFP-negative C8161 metastatic melanoma cells, we used flow cytometry to determine whether sorting of Mart-1:GFP-positive cells after exposure to NGF (72 h) would maintain long-term Mart-1 expression." (PMID 29175861, 2018). "Interestingly, trends in gene expression changes showed that NGF-induced Mart-1:GFP-positive cells were similar to C81-61 non-metastatic melanoma cells, and RA-induced Mart-1:GFP-positive cells showed very little change from C8161 cells." (PMID 29175861, 2018). "Interestingly, both cell lines expressed NGF, with higher expression in C8161 metastatic versus C81-61 non-metastatic melanoma cells." (PMID 29175861, 2018). "On the basis of our findings, CD271 appears to exert its two functions in phenotype switching through distinct modalities: First, heterodimerization of CD271 with the Trk-A receptor, which mediates NGF signaling, specifically affects melanoma cell invasiveness, but not proliferation." (PMID 29215016, 2017). "Furthermore, a cDNA array comparing three primary melanomas and three melanoma metastases with NHEM showed that NGF, NT-3, NT-4, BDNF, and NRN1-like are not differentially regulated and only NRN1 is ~48-fold elevated in melanoma compared to NHEM." (PMID 27901477, 2017). "Similarly, it was demonstrated in another study that c-Yes tyrosine kinase was activated more in human brain-metastatic melanoma cell lines by stimulation of neurotropin and nerve growth factor, whereas c-Src was not affected." (PMID 20796316, 2010). "In this study, we investigated the expression of NGF, proNGF, TrkA, p75NTR and sortilin by immunohistochemistry in a series of human tissue samples (n = 100), including non-cancerous nevi (n = 20), primary melanomas (n = 40), lymph node metastases (n = 20) and distant metastases (n = 20)." (PMID 35457078, 2022).